POU2F1 (POU class 2 homeobox 1)
Description:
Transcription factor that binds to the octamer motif (5'-ATTTGCAT-3') and activates the promoters of the genes for some small nuclear RNAs (snRNA) and of genes such as those for histone H2B and immunoglobulins. Modulates transcription transactivation by NR3C1, AR and PGR. (Microbial infection) In case of human herpes simplex virus (HSV) infection, POU2F1 forms a multiprotein-DNA complex with the viral transactivator protein VP16 and HCFC1 thereby enabling the transcription of the viral immediate early genes.
Synonyms: OCT1; OTF1; Oct1Z; oct-1B
Tractability: Small molecule: a high-quality ligand is known. PROTAC: ubiquitination databases record sites on it.
Target class: Transcription factor
Gene: Protein-coding gene on chromosome 1 (167,220,876 to 167,427,345, forward strand). Ensembl gene ENSG00000143190.
Subcellular location: Nucleus
Subcellular location (Human Protein Atlas): Nucleoplasm; Endoplasmic reticulum; Vesicles
Pathways (Reactome):
Gene expression (Transcription): RNA Polymerase III Abortive And Retractive Initiation; RNA Polymerase III Transcription Initiation From Type 3 Promoter; RNA polymerase II transcribes snRNA genes
Developmental Biology: Differentiation of naive CD4+ T cells to T helper 2 cells (Th2 cells)
Immune System: Interleukin-4 and Interleukin-13 signaling
Signal Transduction: Estrogen-dependent gene expression
Gene Ontology:
Molecular function: DNA binding; DNA-binding transcription factor activity, RNA polymerase II-specific; protein binding; RNA polymerase II cis-regulatory region sequence-specific DNA binding; RNA polymerase II core promoter sequence-specific DNA binding; sequence-specific DNA binding; DNA-binding transcription activator activity, RNA polymerase II-specific; DNA-binding transcription factor activity
Biological process: negative regulation of DNA-templated transcription; positive regulation of transcription by RNA polymerase II; positive regulation of miRNA transcription; regulation of transcription by RNA polymerase II; regulation of DNA-templated transcription
Cellular component: nucleus; RNA polymerase II transcription regulator complex; chromatin; nucleoplasm
Genetic constraint (gnomAD): Loss-of-function variants: 12 observed, 76.08 expected, observed/expected ratio (o/e) 0.16, 90% interval 0.1 to 0.26. The upper end of that interval is the gene's LOEUF score, 0.26, which puts it in group 1 of 6, group 1 being the genes least tolerant of losing a copy. Missense variants: 702 observed, 929.94 expected, observed/expected ratio (o/e) 0.75, 90% interval 0.71 to 0.8. Synonymous variants: 355 observed, 367.81 expected, observed/expected ratio (o/e) 0.97, 90% interval 0.88 to 1.05.
Homologues: Orthologues: macaque POU2F1 (99% identical), chimpanzee POU2F1 (99% identical), pig POU2F1 (99% identical), rabbit POU2F1 (97% identical), dog POU2F1 (97% identical), rat Pou2f1 (95% identical), guinea pig POU2F1 (94% identical), mouse Pou2f1 (94% identical), tropical clawed frog pou2f1 (88% identical), zebrafish pou2f1b (67% identical), Caenorhabditis elegans unc-86 (12% identical), Drosophila melanogaster acj6 (12% identical). Paralogues in human: POU2F2 (40% identical), POU2F3 (28% identical), POU3F3 (20% identical), POU3F2 (18% identical), POU3F4 (18% identical), POU3F1 (17% identical), POU6F2 (17% identical), POU5F1 (17% identical), POU5F1B (16% identical), POU6F1 (16% identical), POU4F3 (15% identical), POU1F1 (14% identical), and 5 more.
Diseases named in the same sentence as POU2F1 in open-access papers:
POU2F1 is named in the same sentence as 46 diseases in open-access papers, as found by Europe PMC text mining. Sharing a sentence is not in itself a finding about the gene and the disease. The quoted sentences say what the papers report.
gastric cancer (7 papers, 2017 to 2022). A primary or metastatic malignant neoplasm involving the stomach. "For example, determining the expression level of POU2F1 (Oct-1) in gastric cancer is of an even higher prognostic value than determining the stage (I–IV) of the disease according to AJCC." (PMID 35538282, 2022). "It has been reported that POU2F1 is highly expressed in various types of tumors, including osteosarcoma, gastric cancer, and head and neck squamous cell carcinoma." (PMID 34257651, 2021). "POU domain, class 2, transcription factor 1 (POU2F1) is involved in the development of gastric cancer (GC)." (PMID 34257651, 2021). "Another study which focused specifically on intestinal-type gastric cancer showed that 74% of the 42 gastric carcinoma samples displayed an increasing POU2F1 protein level, respectively." (PMID 28489585, 2017). "POU2F1 is also an independent prognostic factor in gastric cancer." (PMID 34257651, 2021). "Moreover, knockdown of POU2F1 leads to apparent inhibition of tumor proliferation and invasion in head and neck squamous cell carcinoma, gastric cancer, and so on." (PMID 34257651, 2021). "Moreover, aside its ability to induce metastasis and progression of hepatocellular carcinoma upon interaction with POU2F1/OCT1, FAT1 expression has been shown to be up-regulated in metastatic gastric cancer, and patients with FAT1high gastric cancer had worse prognosis." (PMID 31783581, 2019).
osteosarcoma (7 papers, 2017 to 2023). A usually aggressive malignant bone-forming mesenchymal neoplasm, predominantly affecting adolescents and young adults. "For instance, SND1-IT1 accelerates the proliferation and migration of osteosarcoma via sponging miR-665 to up-regulate POU2F1 expression." (PMID 35739527, 2022). "POU2F1 is frequently upregulated in osteosarcoma and is involved in cell proliferation, differentiation and immune and inflammatory processes." (PMID 29147648, 2017). "In recently, lncRNA SND1-IT1 was firstly reported to be highly expressed in osteosarcoma, and its knockdown suppressed the proliferation and metastasis of RB cells via modulating miRNA-665/POU2F1, suggesting SND1-IT1 as a tumor promotor in osteosarcoma." (PMID 34969359, 2021). "In osteosarcoma, TUG1 acted as a ceRNA by sponging miR-9-5p, inducing the upregulation of transcription factor POU2F1 (POU class 2 homeobox 1)." (PMID 29147648, 2017). "Moreover, it diminishes expression of POU class 2 homeobox 1 (POU2F1), thus acting in a TUG1/mir-p-5p/POU2F1-axis in osteosarcoma cells (Saos-2 and U2OS cell lines)." (PMID 29657304, 2018).
colorectal cancer (5 papers, 2021 to 2026). A primary or metastatic malignant neoplasm that affects the colon or rectum. "Higher POU2F1 expression was associated significantly with a shorter overall survival (OS) of colorectal cancer patients in the population (p < 0.001)." (PMID 34997215, 2022). "Cell proliferation and migration as well as EMT were improved by POU2F1 overexpression in colorectal cancer (CRC), and the effects were reversed by POU2F1 knockdown." (PMID 34257651, 2021). "Similarly, the levels of POU2F1 transcripts in 398 colorectal cancer tissues were significantly higher than that in 39 non-tumor colorectal tissues in TCGA (p < 0.01)." (PMID 34997215, 2022).
breast carcinoma (4 papers, 2007 to 2026). "PIK3R1 and PLCG1 are involved in intracellular signaling cascades and their differential regulation is known to be involved in tumorigenesis, while POU2F1 interacts with several known breast cancer-associated proteins (i.e. BRCA1, BARD1 and PARP1)." (PMID 17280605, 2007). "A recent study showed that POU2F1 regulates expression of the EMT genes Twist1, Snai1 and Snai2 under hypoxia-dependent loss of PER2 in breast cancer." (PMID 28489585, 2017). "CONCLUSION: This study first reveals a novel mechanism by which ISO regulates breast cancer metabolism and apoptosis via the miR-874-3p/POU2F1 axis, highlighting ISO’s potential as a dual metabolic-redox intervention agent and providing a new combined therapeutic target for breast cancer." (PMID 41821073, 2026).
head and neck cancer (4 papers, 2014 to 2022). A primary or metastatic malignant neoplasm affecting the head and neck. "For instance, in head and neck cancer, POU2F1 can bind to the promoters of HOXD10 and HOXD11 to activate their transcription, thus promoting tumor progression." (PMID 34257651, 2021). "POU2F1 has been reported to be involved in carcinogenesis and other disease processes by promoting cell proliferation and metastasis, e.g., in type 2 diabetes, head and neck cancer, cervical cancer, and liver cancer." (PMID 32443864, 2020). "POU2F1 activity regulates HOXD10 and HOXD11 to promote proliferative and invasive phenotypes in head and neck cancer." (PMID 36213580, 2022).
atherosclerosis (3 papers, 2023 to 2025). A disease characterized by the build-up of fatty material and calcium deposition in the arterial wall resulting in partial or complete occlusion of the arterial lumen. "In the present study, KEGG analysis showed POU2F1 was involved in lipid and atherosclerosis signaling pathway." (PMID 37370118, 2023). "Additionally, XPO1 and POU2F1 were involved in human T-cell leukemia virus 1 and lipid and atherosclerosis signaling pathways, respectively." (PMID 37370118, 2023).
cervical cancer (3 papers, 2017 to 2020). A primary or metastatic malignant neoplasm involving the cervix. "Together, these data indicated that transcription factor POU2F1 can directly regulate CTHRC1 expression in cervical cancer cells." (PMID 28303973, 2017).
hepatocellular carcinoma (3 papers, 2017 to 2023). A malignant tumor that arises from hepatocytes. "For example, POU2F1 promotes the growth and metastasis of hepatocellular carcinoma through the FAT1 signaling pathway." (PMID 37370118, 2023). "For example, lncRNA CRNDE/miR-539-5p promotes HCC (hepatocellular carcinoma) progression through inhibition of POU2F1." (PMID 34257651, 2021). "Despite recent efforts to understand activities of POU domain class 2 transcription factor 1 (POU2F1), little is known about the roles of POU2F1 in hepatocellular carcinoma (HCC) tumorigenesis and its correlation with any clinicopathological feature of HCC." (PMID 28489585, 2017). "POU2F1 promotes growth and metastasis of hepatocellular carcinoma (HCC) through the FAT1 pathway." (PMID 34257651, 2021).
liver cancer (3 papers, 2016 to 2020). An epithelial or non-epithelial malignant neoplasm that arises from the liver. "miR-449a was negatively associated with CAPN6 and POU2F1 in liver cancer." (PMID 26375440, 2016). "CAPN6 and POU2F1 were positively associated with liver cancer." (PMID 26375440, 2016). "Analysis of flow cytometry showed that knocking down of POU2F1 induced apoptosis rate of liver cancer cell with CAPN6 overexpression to decrease." (PMID 26375440, 2016). "Endogenous CAPN6 and POU2F1 expression in liver cancer cells with miR-449a overexpression were examined." (PMID 26375440, 2016). "CAPN6 and POU2F1 protein and mRNA levels decreased in liver cancer cells with miR-449a overexpression using western blot and real time RT-PCR assays." (PMID 26375440, 2016). "CAPN6 and POU2F1 protein levels were overexpressed in liver cancer tissues compared with the normal ones." (PMID 26375440, 2016). "Interestingly, most recent studies on the POU2F1 gene have focused on its regulatory impacts on liver cancer." (PMID 32443864, 2020). "In another liver cancer cell line (HepG2),Deopen recovers POU2F1 which could promote cell proliferation and inhibit apoptosis ofliver cancer cells." (PMID 29069282, 2018). "Here, we continue to investigate the regulation of CAPN6 and POU2F1 in liver cancer by miRNAs." (PMID 26375440, 2016). "We have demonstrate previously that POU2F1 regulates CAPN6 expression in liver cancer cells." (PMID 26375440, 2016). "Next, given the fact that CAPN6 and POU2F1 promotes cell proliferation and induce apoptosis resistance in cancer cells, we want to know whether miR-449a suppresses cell proliferation and apoptosis in liver cancer cells by targeting POU2F1 and CAPN6." (PMID 26375440, 2016). "The study indicated that miR-449a functions as a tumor inhibitor in liver cancer by decreasing POU2F1 and CAPN6 expression in liver cancer." (PMID 26375440, 2016). "Our data demonstrated that miR-449a inhibited liver cancer progression by targeting both CAPN6 and POU2F1." (PMID 26375440, 2016). "Our previous study shows that Calpain 6 (CAPN6) expression is regulated by PI3K-Akt in liver cancer through POU2F1 and CAPN6 which promote cell proliferation and inhibit apoptosis of liver cancer cells." (PMID 26375440, 2016). "miR-449a has the influences on liver cancer cell behavior partially by down-regulation of CAPN6 and POU2F1." (PMID 26375440, 2016). "In our study, we identified that CAPN6 or POU2F1 are targets of miR-449a and there was an inverse correlation between miR-449a and CAPN6 or POU2F1 in liver cancer tissue specimens." (PMID 26375440, 2016). "Hoechst staining showed that miR-449a could induce a significant apoptosis including nuclear fragmentation and chromosomal condensation in the liver cancer cells, however, in the cells with miR-449a and CAPN6 or POU2F1 overexpression, the apoptosis was attenuated." (PMID 26375440, 2016).
bladder cancer (2 papers, 2017 to 2021). "Analyses of public databases indicated that POU2F1 exhibited higher expression in renal, ovarian, and esophageal cancers while lower expression in the cerebral tumor, bladder cancer, and liposarcoma, compared with NCs." (PMID 34257651, 2021). "Analyses of databases revealed that POU2F1 showed higher expression levels in kidney, ovary, and esophageal cancer, which was compared to normal controls, whereas expression of POU2F1 in some brain tumors, bladder cancer, and liposarcoma was reduced." (PMID 28489585, 2017).
colon carcinoma (2 papers, 2022 to 2025). "Upregulation of POU2F1 activity was also associated with worse prognosis and oxaliplatin resistance in colon cancer." (PMID 39622638, 2025). "We found that up-regulated POU2F1 expression was associated with worse prognosis and oxaliplatin resistance in colon cancer." (PMID 34997215, 2022). "In this study, we found that POU2F1 expression was up-regulated in colon cancer, and associated with worse prognosis." (PMID 34997215, 2022). "To further understand the biological significance and mechanisms underlying the action of POU2F1 in colon cancer, we investigated how POU2F1 silencing could alter mRNA transcription in SW620 cells by RNA-sequence analysis." (PMID 34997215, 2022). "To understand the role of POU2F1 in colon cancer, we analyzed the expression of POU family members in the GEO datasets." (PMID 34997215, 2022). "More importantly, POU2F1 or ALDOA also enhanced the oxaliplatin resistance in colon cancer cells in vitro." (PMID 34997215, 2022). "POU2F1 over-expression significantly mitigated the H2O2-increased intracellular ROS levels while POU2F1 silencing had opposite effects on colon cancer cells (p < 0.05)." (PMID 34997215, 2022). "POU2F1 can also promote glycolytic metabolism and mitotic stability by promoting poised gene expression in colon cancer cells." (PMID 34997215, 2022). "Mechanistically, POU2F1 directly bound to the ALDOA promoter to enhance the ALDOA promoter activity in colon cancer cells." (PMID 34997215, 2022). "We are interested in further investigating the molecular mechanisms by which the POU2F1-ALDOA axis regulates the chemoresistance in colon cancer." (PMID 34997215, 2022). "Clearly, POU2F1 was paralleled with ALDOA expression in colon cancer cells and both of them acted as oncogenic factors to enhance the malignant behaviors of colon cancer." (PMID 34997215, 2022). "The effects of altered POU2F1 expression on proliferation, glucose metabolism and oxaliplatin sensitivity of colon cancer cells were tested." (PMID 34997215, 2022). "Kaplan–Meier analysis displayed that high-POU2F1 expression was significantly associated with a shorter progression-free survival (PFS) and OS of colon cancer patients (p < 0.001)." (PMID 34997215, 2022). "In this study, we employed the gain and loss of function strategies to determine the roles of POU2F1 and/or ALDOA in the glucose metabolism, proliferation and drug resistance of colon cancer in vitro and in vivo." (PMID 34997215, 2022). "Together, these data indicated that POU2F1 enhanced the survival, proliferation, and clonogenicity of colon cancer cells by up-regulating ALDOA expression, enhancing the glycolysis and PPP activity, but attenuating the DNA damage-induced apoptosis." (PMID 34997215, 2022). "In contrast, POU2F1 or ALDOA deficiency had opposite effects and increased the frequency of apoptotic colon cancer cells." (PMID 34997215, 2022). "In our study, we found that POU2F1 or ALDOA over-expression not only reduced intracellular ROS, but also decreased γ-H2AX, a hallmark of DNA damage-related apoptosis in colon cancer cells." (PMID 34997215, 2022). "The POU2F1 expression was analyzed in GEO dataset, TCGA cohorts and human colon cancer tissues by bioinformatics and immunohistochemistry." (PMID 34997215, 2022). "This study explored the effect of POU domain class 2 transcription factor 1 (POU2F1) on metabolic reprogramming in colon cancer." (PMID 34997215, 2022). "Next, we tested the impact of altered POU2F1 expression on malignant behaviors of colon cancer cells." (PMID 34997215, 2022). "Consistently, seahorse analysis revealed that POU2F1 over-expression enhanced the glycolysis, whereas POU2F1 silencing reduced it in colon cancer cells." (PMID 34997215, 2022). "Moreover, the levels of POU2F1 expression were correlated with ALDOA expression in 184 colon cancer tissues (R = 0.655, p < 0.001) and in colon cancer cell lines." (PMID 34997215, 2022).